CD34 (CD34 molecule)
Diseases named in the same sentence as CD34 in open-access papers (continued):
Sharing a sentence is not in itself a finding about the gene and the disease.
hemangiopericytoma (32 papers, 2007 to 2025). An antiquated term that refers to benign or malignant mesenchymal neoplasms characterized by the presence of neoplastic spindle-shaped to round cells arranged around thin-walled branching vascular spaces. "Ki67 labelling index (p = 0.003) and CD34 expression (p = 0.025) were significantly correlated with the hemangiopericytoma phenotype." (PMID 30183767, 2018). "Focal positivity for cytokeratin and EMA is usually exhibitedby Synovial sarcomas, while hemangiopericytomas exhibit immunopositivity for CD34 and EMA." (PMID 25364427, 2014). "The diffuse CD34 staining pattern found in hemangiopericytomas is very helpful in differentiating them from glomus tumors." (PMID 23050181, 2012). "Hemangiopericytomas are more cellular and are focally and weakly positive for CD34 compared to STFs." (PMID 19893953, 2009). "About half of hemangiopericytomas are CD34 immunoreactive, at least focally." (PMID 25648160, 2015). "The presence of focal CD34 expression and diffuse nuclear STAT6 expression supported the diagnosis of hemangiopericytoma in our clinical case." (PMID 40099070, 2025). "The histopathology findings showed hemangiopericytoma and STAT6 and CD34 positivity after the first and second surgeries." (PMID 37554166, 2023). "In fact, some GISTs display a hemangiopericytoma-like growth pattern, and similar to GIST, both hemangiopericytoma and SFT can express CD34." (PMID 35885469, 2022). "It is particularly difficult to differentiate it especially from hemangiopericytoma (HPC) that has similar histological findings and CD34 positivity." (PMID 23662242, 2013). "Immunohistochemistry showed a positive reaction towards the following markers: CD34, actin and factor VIII, yielding the diagnosis of hemangiopericytoma." (PMID 22499385, 2012). "Hemangiopericytoma is one of the lesions that bears a close resemblance with SFT of soft tissues (fascicular pattern, fibrosis, and vimentin, CD34, and bcl2 immunoreactivity)." (PMID 17577399, 2007). "JGCT was classified as hemangiopericytoma before, and had a hemangiopericytoma-like growth pattern; however, current studies found that hemangiopericytoma did not have the thick-walled vessels and polygonal cells and was CD34 and SMA negative." (PMID 33995279, 2021). "The only STAT6-negative case displayed the characteristic features of the hemangiopericytoma phenotype and was partially positive for CD34 (40%)." (PMID 30183767, 2018). "Hemangiopericytomas are positive for vimentin and CD34, but negative for cytokeratin and smooth muscle markers." (PMID 24386948, 2014). "Strong CD34 immunoreactivity of SFT is especially important in differentiating the neoplasm from hemangiopericytoma, which does not stain as consistently or intensely for CD34." (PMID 24027649, 2013). "Hemangiopericytomas are immunohistochemically positive for vimentin and CD34, but negative for cytokeratin and smooth muscle markers." (PMID 23050181, 2012). "The histopathologic examination and immunohistochemistry staining results (positive for CD34, CD31 and smooth muscle actin, but negative for CD99, S100, B-cell lymphoma 2 (bcl-2) and desmin) confirmed the diagnosis of hemangiopericytoma." (PMID 29785407, 2018).
angina (31 papers, 2010 to 2025). "Intramyocardial delivery of autologous CD34+ cells improves angina frequency and exercise time compared with placebo in patients with refractory angina from obstructive CAD." (PMID 40933110, 2025). "Adult stem cell therapy via intramyocardial injection of autologous CD34+ stem cells has been shown to improve exercise capacity and reduce angina frequency and mortality in patients with refractory angina (RA)." (PMID 39337516, 2024). "Although CD34+ cell therapy was demonstrated to be safe, with improvement of exercise tolerance and decreased angina, the results are only suggestive due to the early termination of the trial." (PMID 37443761, 2023). "Only one clinical trial used autologous CD34+ cells (NCT01508910) in patients with refractory angina to analyze their ability to decrease symptoms of angina and increase exercise capacity." (PMID 37443761, 2023). "A second year of follow-up study shows that autologous G-CSF mobilized CD34+ cell transplantation diminishes angina frequency, unwanted heart outcomes, and mortality rates." (PMID 37138792, 2023). "Subsequently, a 24 month follow-up study of ACT34-CMI patients revealed that weekly angina frequency at 24 months was significantly reduced in patients treated with both low- and high-dose CD34+ cells compared with placebo-treated patients." (PMID 36644256, 2022). "The study found a trend toward lower mortality in individuals with no other options and refractory angina who received autologous CD34+ cell treatment at two years, along with durable improvement in angina." (PMID 36660500, 2022). "At two, six, and 12 months, auto-CD34+ patients experienced a relative angina frequency of 0.78 (95% Confidence Interval (CI) 0.63-0.98; P = 0.032), 0.66 (0.48-0.91; P = 0.012), and 0.58 (0.38-0.88; P = 0.011) compared to placebo patients." (PMID 36660500, 2022). "Patients who received both low- and high-dose CD34+ cells experienced a substantial decrease in angina frequency at 24 months (p = 0.03)." (PMID 36660500, 2022). "The phase I double-blinded, placebo-controlled trial included 24 patients with CCS class III (three) or IV (four) angina who were receiving optimal medical care, and it showed initial safety, as well as clinical improvement in the CD34+, treated individuals." (PMID 36660500, 2022). "A systematic review concluded that CD34+ stem cell therapy can be a safe and effective option for patients who have angina refractory to conventional medical treatment and who cannot be revascularized." (PMID 36660500, 2022). "The authors observed improvement in TET at three months (p=0.06), at six months (p=0.22), at 12 months (p=0.43), and angina frequency at six months (p=0.02) in the CD34+ group." (PMID 36660500, 2022). "Cell therapy using autologous stem cells expressing Cluster of Differentiation 34 plus (CD34+) offers a special therapeutic choice for individuals with refractory angina, seeing as CD34+ stem cells can restore microcirculation." (PMID 36660500, 2022). "In stable angina patients, percentage of circulating CD34+/VEGFR2+ EPCs and artery flow-mediated dilation in Subjects with high depression or stress score were significantly lower than that in subjects with normal depression or stress score." (PMID 34421539, 2021). "The phase 1, double-blinded, placebo-controlled trial enrolled 24 patients with CCS class 3 or 4 angina on optimal medical treatment, and demonstrated initial safety as well as clinical improvement in the CD34+ treated patients." (PMID 34066713, 2021). "In stable angina patients, the percentage of circulating CD34+/VEGFR2+ EPCs and artery flow-mediated dilation in Subjects with high depression or stress score were significantly lower than that in subjects with normal depression or stress scores." (PMID 34421539, 2021).
angina (continued). "Patients with refractory angina who are suboptimal candidates for further revascularization have improved exercise time, decreased angina frequency, and reduced major adverse cardiac events with intramyocardial delivery of CD34+ cells." (PMID 32531108, 2020). "An essential finding in the present study was that, as compared with group 2 patients, the degrees of angina and HF severity were significantly and continuously improved in group 1 patients after CD34+ cell therapy." (PMID 32272750, 2020). "Very recently, a large patient-level pooled analysis of RCT including 304 RA patients has demonstrated consistent and durable improvements in exercise capacity, angina frequency and mortality after intramyocardial injection of autologous CD34+ cells." (PMID 30217223, 2018). "In support of this approach, a meta-analysis of three clinical trials conducted between 2007 and 2016 demonstrated that intramyocardial injection of autologous CD34+ adult stem cells improved exercise capacity, reduced angina frequency, and reduced mortality in RA patients." (PMID 39337516, 2024). "Another more recent clinical trial further identified previous smoking habit, female gender, lower grades of angina score, and diastolic dysfunction as independent promising predictors of CD34+ cell therapy in patients diagnosed with end-stage diffuse coronary artery disease." (PMID 38612587, 2024). "In a one more general note, it could be said that CD34+ therapy is immune and could be a potent operative regenerative approach for microvascular dysfunction and angina patients." (PMID 37138792, 2023). "In phase I/IIa clinical trial using the NOGATM mapping system, autologous G-CSF mobilized PB-CD34+ therapy improved the frequency of angina, exercise tolerance, and CCS scale, providing preliminary evidence of the immunity and bioactivity of CD34+ cell injection in patients with refractory angina." (PMID 37138792, 2023). "A phase II randomized trial, including 167 RA patients, showed a significant improvement in both angina symptoms and exercised tolerance with intramyocardial injection of autologous CD34+ stem cells over placebo at 6, 12 months with persistent results at 24 months follow-up." (PMID 32823683, 2020). "Using the results of our phase I/II clinical trials, previous smoking habit, female sex, lower grades of angina score, and diastolic dysfunction were identified to be independently predictive of “good response” to CD34+ cell therapy in the patients with EnD-CAD." (PMID 32727585, 2020). "Adjusted models, correcting for sex, age, GFR, history of CVA, history of MI or Angina, presence of ulcers, higher triglyceride levels, and cholesterol levels, show higher HRs for PB PC numbers than unadjusted models (CD34+: HR = 0.71, p = 0.07, CD133+: HR = 0.64, p = 0.012)." (PMID 30929097, 2019). "Besides, CD34+ cell administration in patients with varying degrees of angina and myocardial ischemia showed significant improvements in angina frequency and exercise tolerance." (PMID 26101528, 2015). "This laid the foundation for the current study that investigated whether IC administration of autologous CD34+ cells would improve cardiac function and symptoms of HF and angina in patients with diffuse CAD and relatively preserved LV systolic function unsuitable for coronary intervention." (PMID 32272750, 2020). "Additionally, growing data from clinical trials, including our recent study, have shown that both circulatory derived and bone marrow derived CD34+ stem cell therapy remarkably improved angina and ischemia-related left ventricular dysfunction, and restored the microvascular blood flow." (PMID 28148896, 2017). "In a 2-center, phase I study (ESCaPE-CMD) evaluating the feasibility and safety of autologous CD34+ stem cells in patients with ANOCA and CMD, cell therapy improved CFR, angina frequency, angina class, and QoL." (PMID 40933110, 2025).
angina (continued). "When CD34+ cells were injected intramyocardially into patients with CCS functional class III-IV angina who had failed conventional medical therapy and were not revascularization candidates, angina continued to improve two years later." (PMID 36660500, 2022). "Successful phase 1 and phase 2 trials have shown the safety and efficacy of intramyocardial CD34+ stem cell therapy in treating no-option refractory angina." (PMID 34066713, 2021). "Safety and feasibility of intramyocardial injection of autologous CD34+ stem cells were demonstrated in a Phase I/IIa double-blind, randomized controlled trial on 24 RA patients, showing potential bioactivity with improvement in CCS angina class." (PMID 32823683, 2020). "The symptoms of angina and dyspnea were significantly improved in group 1 patients treated with CD34+ cells but not in group 2 patients treated with standard medications at time points of 1, 3, 6 and 12 months." (PMID 32272750, 2020). "The responders had significantly lower angina severity and insignificantly less dyspnea compared with the non-responders prior to CD34+ cell therapy." (PMID 32727585, 2020). "In a previous clinical study, increased expression of specific cardiac markers (Nkx2-5, gata-4, and mef2c) in PBMNCs, and increased number of CD34+/CXCR4+ and CD34+/CD117+ stem cells in PB were observed in ST-elevated MI patients compared to patients with stable angina and healthy Controls." (PMID 30485279, 2018). "We evaluated the mobilization of CD34+CXCR4+ cells in acute MI in comparison to patients with stable angina and control group without CAD." (PMID 22547906, 2012). "Furthermore, in a prospective, double-blind, randomized, phase II study of refractory angina, autologous G-CSF mobilized CD34+ therapy considerably decreased angina frequency and upgraded exercise endurance, angina onset time, and CCS classification without any adverse cardiovascular side effects." (PMID 37138792, 2023). "Nevertheless, traditional EPC populations, such as CD34+VEGFR-2+ and CD34+VEGFR-2+CD133+, are not related to severity of CAD or clinical outcome in the patients with acute coronary syndrome and unstable angina." (PMID 26237060, 2013).
leiomyosarcoma (31 papers, 2010 to 2025). An uncommon, aggressive malignant smooth muscle neoplasm, usually occurring in post-menopausal women. "Immunohistochemical staining shows an expression of SMA, muscle-specific actin, and desmin in most leiomyosarcomas, and expression of S-100 protein, CD34, Ki-67, myogenin, and cytokeratin has also been reported in some cases." (PMID 34544483, 2021). "The aim of this study was to assess microvessels density (MVD) in tumors tissues of uterine leiomyosarcomas using immunohistochemical staining with anti-CD34 antibody." (PMID 26161403, 2015). "In their report, these dedifferentiated leiomyosarcomas lacked the characteristic immunohistochemical staining of differentiated leiomyosarcoma for muscle-specific actin, smooth muscle actin, desmin, and CD34." (PMID 25580348, 2014). "The tumors are definitively diagnosed with histopathology and immunohistochemistry, with leiomyosarcoma showing actin and desmin positive reactivity consistent with smooth muscle cell origin and CD117, CD34, PDGFRA, and DOG1 negativity." (PMID 38915340, 2024). "Leiomyosarcoma usually lacks staining for CD117, CD34 and kit which are positive in the majority of GISTs." (PMID 34143361, 2021). "Primary leiomyosarcomas arise from the muscularis propria layer of the intestinal wall and show immunopositivity DC117, CD34, and CK AE1/AE3." (PMID 24716034, 2014). "From a histological perspective, both GISTs and leiomyosarcomas share similar features, so a definitive diagnosis relies on immunohistochemical data: a vast majority of GISTs express c-KIT protein (CD117) and CD34, whereas leiomyosarcomas often express desmin and smooth muscle actin." (PMID 37395913, 2023). "On the contrary, leiomyosarcomas of the colon were all negative for CD34 and c-kit but most of them showed positivity for SMA, desmin, or both." (PMID 30654838, 2019). "In fact, leiomyosarcomas are composed of cells that consistently express smooth cell actin and desmin, but they are negative for CD34 and CD117, these last are positive in the case of GIST." (PMID 27633779, 2016). "Immunohistochemistry of retroperitoneal leiomyosarcoma shows positive for SMA and desmin and negative for CD117, S-100, HMB45 and CD34, which are of benefit to differentiate leiomyosarcoma from other soft tissue tumors." (PMID 24396471, 2014). "These were 7 tests for h-caldesmon (for leiomyosarcoma), 3 CDK4 (for WDL/DDL), 2 DOG1 (for GIST), 2 beta-catenin (for fibromatosis), 1 each of CD34 (DFSP), desmin, myogenin (rhabdomyosarcoma (RMS)), p63 (sarcomatoid carcinoma), PSAP (prostatic carcinoma), and TLE1 (synovial sarcoma)." (PMID 25165418, 2014). "However, extended immunohistochemical studies later demonstrated diffuse positivity for DOG1 and smooth muscle actin (SMA), with negative staining for CD117, CD34, S100, and desmin, raising suspicion for a leiomyosarcoma-type gastric stromal tumor." (PMID 41209937, 2025). "Finally, we confirmed the expected overexpression of some genes: KIT and ANO1/DOG1 in GISTs, MDM2 and CDK4 in non-myxoid/round cells liposarcomas, CALD1 and tropomyosin genes (TPM1, TPM2) in leiomyosarcomas, PDGFB in DFSPs, MUC1/EMA in synovial sarcomas, and CD34 in SFTs." (PMID 23734203, 2013). "Immunohistochemical staining of spinal leiomyosarcomas showed positive expression of tumor cell SMA and vimentin, negative expression of CD34 and EMA, and focal weakly positive expression of the S-100 protein." (PMID 36520263, 2022). "In our case differentiation between GIST, leiomyosarcoma and PEComa was based on immunohistochemical ground with CD117, CD34 showing negative results and positive HMB-45." (PMID 25896860, 2015). "In contrary, secondary leiomyosarcomas arise from the mucosal layer of the intestinal wall and are negative for DC117, CD34, and CK AE1/AE3." (PMID 24716034, 2014).
leiomyosarcoma (continued). "Besides, in these two cases, the sarcomatous element exhibited undifferentiated spindle cells and differentiated leiomyosarcoma, respectively; the histopathologic results revealed few vascular components and IHE results revealed negative CD34 expression in the two tumors." (PMID 29482629, 2018).